MIR5004 (microRNA 5004)
Synonyms: hsa-mir-5004; mir-5004
Gene: MicroRNA gene on chromosome 6 (33,438,331 to 33,438,437, forward strand). Ensembl gene ENSG00000284256.
Homologues: Orthologues: macaque MIR5004 (100% identical).